HIF1A (hypoxia inducible factor 1 subunit alpha)
Diseases named in the same sentence as HIF1A in open-access papers (continued):
Sharing a sentence is not in itself a finding about the gene and the disease.
tumor (continued). "Overexpression of miR-183 or inhibition of IDH2 can contribute to the up-regulation of HIF-1α and its downstream molecule GLUT1 so as to facilitate glucose uptake and glycolysis process in tumor cells." (PMID 26934324, 2016). "Evidence suggests that HIF-1α activation regulates VEGF gene expression, indicating a direct interaction between these two tumor markers." (PMID 26951793, 2016). "Previous studies have shown the importance of p70S6K1/HIF-1α/VEGF pathway in the regulation of angiogenesis and tumor progression." (PMID 27765914, 2016). "In line with hypoxia-induced tumor malignancy, DNA hypermethylation at the promoter of PHD3 and VHL, two enzymes involved in destabilization of the HIF-1α protein, is observed in multiple myeloma and B-cell lymphoma." (PMID 26861406, 2016). "HIF protein, especially HIF-1α and HIF-2α, are correlation with tumor development, metastasis and promote epithelial-mesenchymal transition." (PMID 27456341, 2016). "It has been shown that Nrf2 silencing blocks HIF-1α-dependent VEGF expression in HT29 colon cancer and suppresses tumour growth with a concomitant reduction in VEGF-induced angiogenesis in mouse xenograft models." (PMID 26697129, 2016). "Our animal study revealed that HEGU inhibited the expression of Ki67, CD45, CD31, VEGF-A, HIF-1α, iNOS, and COX-2 in tumor tissues and plasma levels of VEGF-A, MMP-9, ICAM, and VACM." (PMID 27314329, 2016). "In NSCLC cell xenograft model, either overexpression of miR-206 or inhibition of 14-3-3ζ inhibited the STAT3/HIF-1α/VEGF pathway and decreased the tumor growth and angiogenesis." (PMID 27806334, 2016). "In our preliminary study on a small series of 7 HNSCC samples, we found that in necrotic tumors the hypoxic markers CAIX and HIF-1α were expressed adjacent to the necrotic areas, whereas TLR3 was detected in the periphery of the tumor, on the invasion front." (PMID 27791989, 2016). "To study the expression of angiogenesis-related molecules we performed immunohistochemistry analysis of HIF1α, HIF2α, VEGF, VEGFR1 and VEGFR2, both in tumor and in peritumoral tissue of GBM surgical samples." (PMID 27705944, 2016). "A previous study showed that c-MYC together with HIF-1α induced the overexpression of VEGF, leading to tumor angiogenesis." (PMID 27483433, 2016). "The HO-1 inhibitor, ZnPP, possessed the properties of anti-tumor agent by decreasing HIF-1α levels, blocking VEGF production, impairing tumor angiogenesis, and inhibiting tumor growth." (PMID 26822586, 2016). "In fact, a previous report showed that endogenous ROS regulated the HIF-1α and VEGF expression in cancer cells, hence controlling the angiogenesis and tumor development in vivo." (PMID 27286448, 2016). "miR-17-92 and miR-192 inhibited the progression of cancers via suppressing tumour angiogenesis through targeting multiple tumour angiogenesis-inducing genes, TGFBR2 (transforming growth factor, beta receptor 2), HIF1α and VEGFA in vivo and in vitro." (PMID 27213336, 2016). "Meanwhile, the overexpression of HIF-1α can rescue the anti-tumor effect of RPS7, suggesting HIF-1α to be a potential target gene of RPS7." (PMID 26735579, 2016). "In the present study, the expression of HIF-1α and its downstream targets VEGF-A, COX-2, VEGF-R2, and iNOS were reduced in tumor tissue treated with HEGU or licoricidin." (PMID 27314329, 2016). "We measured the protein levels of HIF-1α and HIF-2α in the 36 matched pairs of ccRCC tumor and adjacent normal tissues by immunoblotting." (PMID 27741516, 2016). "Both HIF-1α and HIF-2α have been observed to be expressed at higher levels in HCC tissues than those in matched, non-tumor-surrounding tissues." (PMID 27094811, 2016).
tumor (continued). "We found that the growth of the NSCLC tumor xenografts was inhibited by PD98095, while immunohistochemical staining showed that HIF-1a and CD34 expression was significantly decreased." (PMID 27456341, 2016). "Our results suggest that RPS7 plays as a tumor suppressor to inhibit the growth and glycolysis of CRC by suppressing HIF-1α." (PMID 26735579, 2016). "Notwithstanding a modest (20-30%) reduction in the mRNA levels of HIF-1α and its downstream target genes VEGF and BNIP3, we observed significant differences in tumor growth between silenced DTC and control cells." (PMID 27105499, 2016). "Oral administration of HEGU decreased the expression of hypoxia-inducible factor-1α (HIF-1α) and the HIF-1α target genes inducible nitric oxide synthase (iNOS) and cyclooxygenase-2 (COX-2) in tumor tissues." (PMID 27314329, 2016). "The reduced tumor-initiating and invasive potential in the CD49fNeg/Low PyMT or MDA-MB-231 cells overlaps with phenotypes in Hif1a null PyMT tumors or HIF1A knockdown in MDA-MB-231 tumor cells." (PMID 27001172, 2016). "Rac1 activity was documented to be required for hypoxia-inducible factor 1α (HIF-1α) activation and VEGF expression elevation, which promoted angiogenesis, microscopic venous invasion, and tumor invasiveness of HCC." (PMID 26933917, 2016). "Importantly, tumor cells may also express alarmin receptors following hypoxia and HIF1α activation." (PMID 26798421, 2016). "We assessed the levels of NQO1 and HIF-1α in these tumours and found that NQO1 knockdown tumours showed significantly reduced HIF-1α expression, which was associated with decreased proliferation (Ki67) and elevated apoptosis (cleaved caspase 3, CC3)." (PMID 27966538, 2016). "HIF-1α, a master regulator of cellular hypoxic response, is a transcription factor essential for the transcriptional activation of VEGF, resulting in tumor angiogenesis." (PMID 27271600, 2016). "HIF1α triggers both, VEGF secretion, and the expression of glycolytic markers which exert influence on the glycolytic rate in tumor cells." (PMID 27626684, 2016). "Further in vitro and in vivo experiments demonstrated the tumor suppressor role of CPS1-IT1: it reduced tumor growth and metastasis by decreasing Hsp90 binding to and activation of HIF-1α, thereby inhibiting the epithelial-mesenchymal transition." (PMID 27248828, 2016). "To analyze tumor formation, we used two different tumor models in C57BL/6J wt, Hif-1αLysM−/−, Hif-2αLysM−/−, and Hif-1α/2αLysM−/− mice." (PMID 27015123, 2016). "This suggests that some tumour-derived and secreted molecules can mediate VEGF and ARG1 expression in macrophages through a mechanism involving HIF1α stabilization under normoxic conditions." (PMID 27083002, 2016). "This outcome was mediated through miR-210-directed effects on HIF-1α and a resultant increase in GLUT-1 and MCT4, glucose and lactose membrane transporters (respectively) capable of secreting growth factors to promote tumor growth." (PMID 25809609, 2015). "Specifically, re-expression of HIF-1α in CCRC lines that lack wild-type HIF-1α slows growth, whilst overexpression of HIF-2α accelerates growth in tumor xenografts." (PMID 26262842, 2015). "These molecules have been reported to increase HIF-1α accumulation and to regulate hypoxia-inducible gene expression, thus promoting VEGF transcription and translation and resulting in tumour angiogenesis." (PMID 26146622, 2015). "This adaptive change relies considerably on the increase in the stability of hypoxia inducible factor 1 alpha subunit (HIF1A), which is negatively regulated by the von Hippel-Lindau (VHL) tumor suppressor." (PMID 26439688, 2015). "In a further in vivo experiment, the tumor formed by cells co-transfected with SOCS3 and HIF-1α exhibited a higher growth rate and level of angiogenesis compared with that of cells transfected with Ad5-SOCS3 only." (PMID 25695729, 2015).
tumor (continued). "Hypoxia in growing tumors stabilizes HIF1α to up-regulate VEGF expression, which in turn stimulates tumor angiogenesis." (PMID 26287601, 2015). "This was effective in RKO cells in which pharmacological inhibition of hypoxia-inducible factor 1-alpha (HIF-1α) with echinomycin increased OCR, decreased tumor pO2, and increased the activity of the HAP, tirapazamine." (PMID 25635223, 2015). "The influences of OA on the protein expressions of HIF1α, SIRT3, and SOD2 in tumor tissue of the nude mice inoculated with MCF-7 cells were consistent with that inoculated with MDA-MB-231 cells." (PMID 25855962, 2015). "Recently, HER2 signaling was reported to increase the synthesis rate of HIF-1α protein and thus enhance VEGF-mediated abnormal tumor angiogenesis." (PMID 26625311, 2015). "Our study provides new mechanistic insight that TEPA inhibits tumor progression through reversal of EMT and down-regulation of HIF1-α-Snail/Twist signal pathway." (PMID 26174737, 2015). "In this study, we found that the expressions of HIF-1α, CXCR4 and SDF-1α were co-localized in the peripheral region of necrotic tumor tissues, which were relatively hypoxic due to reduced blood flow." (PMID 25843954, 2015). "In conclusion, we showed that increased expression of HIF-1α and CXCL8 in HCC correlate with tumor progression, metastasis and, a poor survival." (PMID 26078356, 2015). "In this systematic review, we identified HIF-1a, HIF-2a, CA-IX, GLUT-1, and OPN as the best studied endogenous markers of tumor hypoxia." (PMID 25919147, 2015). "Inactivation of NF-κB, STAT3, or HIF-1α, neutralization of CCL2 or CXCL12, or TAM depletion results in disrupted angiogenesis and decreased tumor growth, highlighting the critical role of inflammatory mediators in tumor angiogenesis." (PMID 26501341, 2015). "We demonstrated that S1P neutralization created a less hypoxic environment as shown by the marked decreased in HIF-1α expression and activity (concomitant decrease in GLUT-1 expression), and secretion of VEGF from the tumor." (PMID 25915662, 2015). "We here show that HIF-1α regulates the SHH pathway in NB and further influences the growth and progression of the tumor." (PMID 25811359, 2015). "The current study aimed to determine the expression of hypoxic markers, including HIF-1α, CA9, GLUT1, and VEGF, in STS using immunohistochemistry, and to analyze the impact of overexpression on the clinicopathological features of tumor aggressiveness." (PMID 25789026, 2015). "We found that auraptene abolished HIF-1α protein translation and reduced transcription of HIF-1α target genes, including GLUT2, HK2 and LDHA, which are involved in regulating tumor metabolism." (PMID 26474388, 2015). "In another example, MD simulation has deciphered the dynamic interaction between two tumor-related molecules, VHL and hypoxia-inducible transcription factor 1α (HIF1α) where distant two VHL regions are involved in its binding to HIF1α." (PMID 25781978, 2015). "LOX and HIF-1α overexpression were observed in hypoxic EOC cells, with expression levels correlating significantly with metastasis and tumor stage in EOC." (PMID 26579497, 2015). "Research has shown that HIF-1α antagonists, such as EZN-2968 and PX-478, inhibit tumor cell proliferation in vitro and in vivo." (PMID 25733977, 2015). "Thirdly, at the molecular level Klf5 deletion significantly elevated the expression of HIF1α and its pro-angiogenic functional effectors such as VEGF and PDGF, which represent the most potent inducers of tumor angiogenesis." (PMID 25896712, 2015). "Upon deletion of VHL in tumor-specific CD8+ T cells, hypoxia modulates expression of effector molecules through HIF-1α and 2α to enhance function and control of persistent viral infection and tumor growth." (PMID 26393659, 2015). "The HIF-1α/SDF-1/CXCR4 pathway governs the primary and metastatic tumor microenvironments and organ-specific metastases in different malignancies." (PMID 26517240, 2015).
tumor (continued). "UPR activity also plays a role during tumor development, and the angiogenic switch was reported to be induced by the PERK/ATF4 pathway in a HIF1α independent manner." (PMID 26000250, 2015). "It has been reported that hypoxia is involved in regulating miR-210, miR-34a, miR-17/20a and others miRNAs that contribute to tumor growth, the epithelial-mesenchymal transition (EMT) and myeloid leukemic cell differentiation via HIF1α." (PMID 25714028, 2015). "In contrast, these independent changes in Stat3 and HIF-1α induced by tanshinone-1 synergistically inhibit the tube formation of endothelial cells and the VEGF secretion from tumor cells." (PMID 26202747, 2015). "The eIF family proteins are also key regulators of tumor angiogenesis that function by upregulating angiogenic factors such as VEGFA and HIF1α." (PMID 25993439, 2015). "The CD49fhiCD24hi subpopulation most significantly differed from the tumor of origin, with reduced expression observed in the majority of HIF-1α inducible glycolytic genes, as well as HIF-1α-independent glycolytic genes." (PMID 26316122, 2015). "Through decreasing the production of HER2 protein, metformin induced a similar effects as AG825 on suppressing HER2 phosphorylation, thus restraining the activity of HIF-1α-VEGF signaling axis and suppressing tumor angiogenesis in vivo." (PMID 26625311, 2015). "These drugs have been shown to inhibit HIF1A, and PI3K and mTOR are here suggested as potential targets in cases with tumor necrosis." (PMID 26485755, 2015). "We found high expression of HIF-1α in tumor tissues from NSCLC patients, indicating that hypoxia in solid tumors was involved in the tumor microenvironment." (PMID 26553068, 2015). "There were also relationships of HIF-1α with pTNM, TFG scale, invasion depth and mode, tumor recurrences, and overall survival (p < 0.05)." (PMID 25412955, 2015). "HIF-1α, β-catenin, uPA and MMP-7 protein expression levels were highest in the tumor tissue from the hypoxia group and lowest in the interference group." (PMID 25997455, 2015). "Stabilization of HIF-1α allows regulation of genes involved in angiogenesis such as VEGF, which is secreted from the tumor, attracting endothelial cells by binding to their surface VEGF receptors thus allowing increased tumor vascularization and growth." (PMID 26010887, 2015). "Although bortezomib blocks the degradation of HIF-1α in the proteasome, the accumulating HIF-1α is unable to activate an effective hypoxia response, rendering tumor cells vulnerable to a hostile hypoxic microenvironment." (PMID 26416246, 2015). "HIF-1α also regulates many cancer signaling pathways, including PI3K/AKT/mTOR, Notch, and Myc, to mediate tumor proliferation, invasion and migration." (PMID 25993275, 2015). "Some studies have shown that miRNA-20b modulates HIF-1α and VEGF to keep tumor adapting to different environment and promoting cell division, proliferation, and migration." (PMID 26612965, 2015). "Both HIF-1α and HIF-2α proteins are often overexpressed in a variety of human tumors, especially solid tumors, and tumor-derived cell lines." (PMID 25726527, 2015). "HIF-1α is involved in promoting vessel formation through induction of VEGF expression and enhancing tumor growth through upregulation of glycolytic pathway-related genes." (PMID 26474388, 2015). "We suggest that expression of HIF-1α and serum levels of CXCL8 are predictive markers of tumor recurrence and prognosis." (PMID 26078356, 2015). "HIF-1α and ZEB1 are both widely considered as tumor-initiating factors, but our results demonstrate that ZEB1 is a direct downstream of HIF-1α, suggesting a novel molecular mechanism for HIF-1α-inducing EMT and cancer metastasis." (PMID 26057751, 2015). "Overall, both the modalities of 2D and 3D PCA plots supported the effectiveness of HIF-1α and PGK1 expression to define tumor sub-grouping based on differential expression of Notch genes." (PMID 25734817, 2015).
tumor (continued). "Initially identified as a tumor suppressor in breast cancer, SIRT3 maintained the integrity of mitochondria during stress and Hif1α destabilization." (PMID 26317998, 2015). "Peritumoral IL-6, IL-6R, gp130, CD68, and HIF-1α expression, as well as MVD, gradually increased during tumor growth." (PMID 26525581, 2015). "In hypoxic conditions, hypoxia inducible factor-1α (HIF-1α) induced LOX expression and facilitated tumor migration, invasion, and metastasis in a range of cancers." (PMID 26579497, 2015). "Tumour samples were categorized into three groups (high, intermediate and low) according to the expression levels of UCHL1 and HIF-1α, respectively." (PMID 25615526, 2015). "Nevertheless, further studies are needed to better define the role of copper on the functional interaction between GPER, HIF-1α and VEGF in malignant cells and tumor microenvironment." (PMID 26415222, 2015). "In parallel with HIF-1α protein levels, GLUT-1 levels decreased with increasing ascorbate supplementation in both tumor models (P < 0.05)." (PMID 25354695, 2015). "Functional studies showed IL-24 inhibited tumor cell migration and invasion concomitant with reduction in CXCR4 and its downstream targets (pAKTS473, pmTORS2448, pPRAS40T246 and HIF-1α)." (PMID 25775124, 2015). "In a large group of HCC patients, we confirmed that HIF-1α and CXCL8 expression is increased in HCC tissues, compared with adjacent non-tumor liver tissues." (PMID 26078356, 2015). "For patients whose tumor had high levels of both γ-H2AX and HIF-1α had worse over-all survival, so as with high levels of both γ-H2AXand EGFR." (PMID 25537504, 2015). "Tumour samples were categorized into four groups (+++, ++, +, −) according to the expression levels of UCHL1 and HIF-1α, respectively." (PMID 25615526, 2015). "MiR-21 induces tumor angiogenesis through targeting PTEN, leading to activated AKT and ERK1/2 signaling, thereby enhancing hypoxia-inducible factor 1α (HIF1α) and the expression of the vascular endothelial growth factor (VEGF)." (PMID 26116372, 2015). "In the hypoxic microenvironment of solid tumors, HIF-1α expression in certain clones affords a selective advantage through multiple mechanisms that rely on angiogenesis and EMT, which ultimately increases tumor aggressiveness." (PMID 26528854, 2015). "HIF-1α directly activates TWIST to promote the epithelial-mesenchymal transition and tumor metastasis." (PMID 25738958, 2015). "In terms of histochemistry, hypoxia-inducible factor (HIF)-1α is well known to induce vascular endothelial growth factor (VEGF), which in turn correlates with tumor progression." (PMID 26582158, 2015). "Taken together, lactate in tumor microenvironment influenced THP-1 monocytes and increased the expressions of HIF-1α, COX2 and PEPCK." (PMID 25938544, 2015). "In other words, it can be interpreted that high tumor proliferative rate, measured by Ki67 expression, in the context of low SATB1 (and relatively low HIF-1α) expression was an independent predictor of worse OS." (PMID 26512778, 2015). "Hypoxia inducible factor-1α (HIF-1α), induces cytokines such as CXCL8 and tumor dissemination, chemo- and radio-resistance." (PMID 26078356, 2015). "PI3K/AKT/mTOR signaling can increase HIF-1α activity by inducing its stabilization, and we and others have shown that melatonin regulates the PI3K/AKT/mTOR pathway in some tumor types." (PMID 26252771, 2015). "Both HIF-1α and HIF-2α are engaged in the hypoxia–mediated regulation of multiple genes involved in tumor growth and progression." (PMID 26305551, 2015). "Further confirmation on different metabolic pathways in ICM and ESC comes from the observation that PDGFC and HIF1a, which contribute to the expression of LDHA and promote anaerobic glycolysis in tumor cells, were downregulated in bovine ICM cells." (PMID 26681441, 2015). "Thus, it was important to determine whether IMQ stimulated HIF-1α activation in tumor cells." (PMID 24658058, 2014).